CD59 (CD59 molecule (CD59 blood group))
Diseases named in the same sentence as CD59 in open-access papers (continued):
Sharing a sentence is not in itself a finding about the gene and the disease.
prostate carcinoma (continued). "In prostate cancer, PTX3 showed an association with the increased early component of the complement system and a complement inhibitor, CD59, and the authors speculated that the change in inflammatory signal possibly promoted the oncogenic process." (PMID 39594709, 2024). "Our previous research showed that CD59 expression is higher in prostate cancer bone metastases than in primary prostate cancer lesions, which suggests that CD59 may promote prostate cancer metastasis to the bone." (PMID 32337233, 2020). "In some instances, increased expression of CD59 correlates with overall decreased survival rates in patients with colorectal cancer, prostate cancer, and B cell lymphoma while low CD59 expression in breast tumors correlates with increased invasiveness and poor survival." (PMID 33718121, 2020). "However, our results point out that in patients who will subsequently develop a prostate cancer the prostate tissue is characterized by the increased expression of C1q and reduced activation of the Complement system, terminally inhibited by CD59." (PMID 33110136, 2020). "Indeed, we observed a clear up-regulation of CD59 in the patients who will subsequently develop prostate cancer both at the first and at the second biopsy." (PMID 33110136, 2020). "In previous studies, we found higher levels of CD59 expression in bone metastases of patients with prostate cancer than in primary prostate cancer lesions, suggesting that CD59 may play an important role in the metastasis of prostate cancer to the bone." (PMID 32337233, 2020). "Tetranectin showed differential expression in epithelial and stromal cells of prostate cancer and hyperplasia tissues.The expression of CD59 was highest in PC3 and lowest in LNCap, while the expression of haptoglobin and tetranectin was the highest in DU145 and lowest in PC3." (PMID 31413735, 2019). "In our study, mass spectrometry analysis showed that the expression of CD59 in serum of prostate cancer patients with bone metastasis was significantly higher than that in non-metastasis patients, and the results were validated by serum ELISA analysis of a larger sample size." (PMID 31413735, 2019). "Furthermore, the complement inhibitor CD59 was significantly upregulated in prostate cancer." (PMID 41479916, 2025). "We also note that CD59 may be also relevant to reveal the heterogeneous nature of prostate cancer." (PMID 20805891, 2010). "In essence, this study suggests that PTX3, a potential biomarker for distinguishing prostate cancer from BPH, promotes tumor progression by inhibiting the activation of the terminal complement pathway through increased CD59 expression." (PMID 41479916, 2025). "Immunohistochemical analysis revealed the expression of CD59, CD55, and CD46 on uveal melanoma, thyroid carcinoma, lung and kidney cancer, colon adenocarcinoma, and prostate cancer." (PMID 31024572, 2019). "In this context relevant, CAV1 and CD59 are present together with delta-catenin in urinary EVs of prostate cancer patients, whereby delta-catenin was shown to be released to the extracellular matrix thanks to the presence of CAV1 and CD59." (PMID 31362353, 2019). "The previous study found that CD59 molecules are overexpressed in various reproductive system tumors (cervical cancer, prostate cancer, breast cancer, etc.), but the correlation between CD59 and oral squamous cancer has not been reported." (PMID 35387305, 2022). "The immunohistochemical staining showed that CD59 was expressed in bone metastasis tissues and prostate cancer tissues, and almost negative in prostate hyperplasia tissues." (PMID 31413735, 2019). "The mean CD59 concentrations (in ng/mL) in serum of prostate cancer patients with bone metastasis, prostate cancer without metastasis and benign prostatic hyperplasia were 57.94 (± 17.05), 28.92 (± 6.35), and 15.79 (± 5.29), respectively." (PMID 31413735, 2019).
prostate carcinoma (continued). "CD59 was most strongly expressed in bone metastatic tumor of prostate cancer, but rarely expressed in glandular epithelial cells of prostate hyperplasia, which was nearly negative for CD59." (PMID 31413735, 2019). "CD59 is an interesting gene as “a comprehensive investigation of CD59 expression in prostate cancer has not been conducted yet”." (PMID 20805891, 2010). "Similarly, inhibition of CD59 with a monoclonal antibody led to efficient sensitization to CDC of neuroblastoma cells, leukemic cells, breast, ovarian, renal, and prostate carcinoma cells." (PMID 31024572, 2019).
diabetes (20 papers, 2009 to 2025). "In hyperlipidemic mice, the combination of diabetes and CD59 deficiency promoted atherosclerosis in comparison with diabetes alone." (PMID 39518935, 2024). "The protective effects of CD59 are so important that pathogenically low levels of CD59 are associated with autoimmune diseases such as diabetes, multiple sclerosis, and chronic hemolysis." (PMID 31164885, 2019). "Also, erythrocytes of participants with diabetes were more susceptible to complement-related lysis, likely as a result of glycation-induced inactivation of CD59." (PMID 31993713, 2020). "Notably, in the kidney and nerves of participants with diabetes, glycated CD59 co-localised with C5b-9, and presence of glycated, less functional CD59 was considered to be the cause of increased C5b-9 deposition." (PMID 31993713, 2020). "This metabolic rewiring could be crucial for inflammatory conditions where there is chronic complement activation, such as RA where sublytic MAC and increased glycolysis can contribute to inflammation and diabetes, where high levels of glucose cause glycation of CD59 with subsequent MAC activation." (PMID 36248901, 2022). "Here we report that NICC from genetically modified (GM) pigs deleted for αGal and expressing the human complement regulators CD55 and CD59 can cure diabetes long-term in immunosuppressed baboons, with maximum graft survival exceeding 22 months." (PMID 35784286, 2022). "In diabetes, the membrane glycoprotein CD59, which serves as a protective element against complement-mediated lysis, is inactivated by non-enzymatic glycation and shed from the cell membranes into the plasma." (PMID 34658643, 2021). "This plasma-glycated CD59 (pGCD59), measurable by flow cytometry, is used as a diabetes biomarker, and has recently been shown to be specific for GDM determination, even before the 20th week of gestation." (PMID 34658643, 2021). "Regarding pregnancy complications of diabetes, it is conceivable that glycation-inactivation of placental CD59 increases complement-mediated placental damage contributing in part to the multiple complications seen in women with GDM." (PMID 32682411, 2020). "Glycated CD59 was also higher in the circulation of diabetic than of healthy individuals, and was detected in the urine of participants with diabetes." (PMID 31993713, 2020). "The reason for this discrepancy is that although CD59 is very much involved in the diabetes phenotype, it seems to be responsible for the vascular changes that follow from type 2 diabetes." (PMID 19575795, 2009). "Similarly, Acosta and colleagues further clarified the molecular mechanisms linking CD59 dysfunction to complement-mediated vascular injury in diabetes." (PMID 40648962, 2025). "However, hyperglycemia-induced glycation of CD59 in diabetes impairs the protection from complement auto-attack." (PMID 33903634, 2021). "For instance, inherent differences in CD59, as detected here, could have a major impact on the autoimmunity response and tissue degradation during progressive diabetes." (PMID 31133884, 2019). "This phenomenon may indicate that in elderly cancer patients, the benefits of low-levels of CD59 against cancer might counteract the effects of atherosclerosis or diabetes." (PMID 31685825, 2019). "Increased glycosylation has been implicated in inactivation of complement regulators in diabetes, and patients with advanced diabetic retinopathy have a reduction in the complement regulators CD55 and CD59 and increased deposition of MAC in their ocular vasculature." (PMID 24167638, 2013). "A clinical trial revealed that glycated CD59 was independently and positively associated with HbA1c levels, regardless of whether the individual had diabetes or not." (PMID 38671903, 2024). "In diabetes, glycated CD59 is formed by non-enzymatic glycation which inactivates the complement inhibitor CD59." (PMID 36769669, 2023). "In diabetes, non-enzymatic glycation inactivates the complement inhibitor CD59, forming glycated CD59." (PMID 32682411, 2020).
diabetes (continued). "Due to the lack of complement regulatory protein CD59, the development of diabetes-induced atherosclerosis in mice is accelerated." (PMID 33083497, 2020). "In diabetes, CD59 is inactivated by non-enzymatic glycation forming gCD59." (PMID 32682411, 2020). "Likewise, the lowering of plasma glycated CD59 was intimately associated with a reduction in blood glucose, whereas intracellular (i.e., non-secreted) CD59 is required for normal insulin secretion by pancreatic β cells and is downregulated in patients with diabetes." (PMID 39518935, 2024).
atherosclerosis (19 papers, 2011 to 2025). A disease characterized by the build-up of fatty material and calcium deposition in the arterial wall resulting in partial or complete occlusion of the arterial lumen. "Because modification of CD59 as a Creg was also shown in an in vitro study, suggesting enhancement of atherosclerosis, damage to the CD59 protein caused by long-term glucose exposure might affect PD patients." (PMID 39201294, 2024). "The underlying mechanism by which CD59 plays a protective role in the pathogenesis of atherosclerosis remains unclear." (PMID 24319687, 2013). "Furthermore, deficiency of CD59, the primary inhibitor of C5b-9 formation, in apoE−/− mice resulted in enhanced C5b-9 formation leading to endothelial dysfunction, accelerated atherosclerosis, formation of vulnerable plaques, and premature death." (PMID 24278688, 2012). "According to the latest data, CD59+ affects the development of atherosclerosis and cardiac ischemia." (PMID 40564110, 2025). "The LAA mechanism clots demonstrated elevated levels of proteins such as CD59, LAMP1, and ELANE, which are associated with the ubiquitin‐proteasome pathway and the progression of atherosclerosis." (PMID 40079446, 2025). "Phycocyanin promotes the expression of CD59 in mice and delays or inhibits the development of atherosclerosis." (PMID 39296509, 2024). "A deficiency of CD59 in mice models has been shown to accelerate the development of atherosclerotic plaques, suggesting a protective role of CD59 in atherosclerosis." (PMID 31555286, 2019). "The joint actions of the C-PC and CD59 were more effective to inhibit intimal injury and formation of atherosclerosis plaque." (PMID 24319687, 2013). "The effects of C-phycocyanin (C-PC) on atherosclerosis and the regulatory effects of CD59 gene on anti-atherosclerotic roles of C-PC were investigated." (PMID 24319687, 2013). "Transgenic mice expressing a negative regulator of complement, referred to as protectin (CD59), on the endothelium are protected against atherosclerosis." (PMID 21720565, 2011). "Fas protein levels were lower in C-PC treatment group and CD59 transfection group and were the lowest in C-PC+CD59 synergy group which was not susceptible to the formation of atherosclerosis." (PMID 24319687, 2013). "C-PC+CD59 could lower the levels of blood lipids, slow down the formation of hyperlipidemia, and finally inhibit the occurrence of atherosclerosis." (PMID 24319687, 2013). "Thus, for example, lack of CD55 or CD59 in atherosclerosis-susceptible ApoE−/− mice, resulted in worse disease, while CD59 administration reduced the severity of experimental atherosclerosis by abrogating MAC formation." (PMID 31555668, 2019). "Furthermore, combination of high MBL level and hyperglycemia associated with advanced glycation products, fructosamine, altered LDL clearance, and defective CD59 may increase atherosclerosis." (PMID 26640806, 2016). "The results showed that C-PC or CD59 could inhibit the buildup of atherosclerotic plaque to some extent, and the inhibitory effects were more significant in CD59+C-PC synergy group, so CD59+C-PC could further slow down and finally inhibit the formation of atherosclerosis." (PMID 24319687, 2013). "Functionally, CD59 regulates the complement membrane attack complex (MAC) and has been reported to have a protective effect against atherosclerosis by restricting MAC formation." (PMID 28922377, 2017). "Moreover, CD59 transfection could partially reduce blood fat levels, inhibit intimal hyperplasia and buildup of atherosclerotic plaque and further slow down the progress of atherosclerosis." (PMID 24319687, 2013). "Second, CD59 is an identified protein for predicting the LAA mechanism, as it has a regulatory role in complement membrane attack complex assembly for mediating endothelial damage and foam cell formation of the atherosclerosis plaque." (PMID 40079446, 2025).
atherosclerosis (continued). "Proteins including CD59, LAMP1, and ELAN involved in LAA play crucial roles in the survival, proliferation, and migration of macrophages, potentially influencing the development of atherosclerosis in large arteries." (PMID 40079446, 2025).
breast carcinoma (16 papers, 2007 to 2025). "Analysis of 120 breast cancer patients revealed a worse prognosis associated with CD59 overexpression." (PMID 31024572, 2019). "In contrast, another report concluded that loss of CD59 correlated with poor survival in 520 breast cancer patients." (PMID 31024572, 2019). "When CD59 is neutralized, both glutamine-deprived and glutamine-restored breast cancer cells demonstrated increased complement susceptibility." (PMID 17623109, 2007). "Coincidently, the rapidly proliferating glutamine-restored breast cancer cells demonstrated increased complement resistance in association with the increased expression of CD59 and CD55." (PMID 17623109, 2007). "The authors of this finding hypothesize that the loss of CD59 may provide a “selective advantage” for breast cancers, which results in more invasive tumors." (PMID 31164885, 2019). "The loss of CD59 may offer a selective advantage for breast cancers, resulting in more aggressive tumors." (PMID 24904649, 2014). "Beyond its role in inhibiting canonical complement action within the TME, CD59 was shown to impede apoptosis of breast cancer cells, thereby contributing to tumor development." (PMID 40370471, 2025). "CD55 and CD59 expression were also correlated with the protection of HER2-overexpressing breast cancer and uterine serous carcinoma cells from trastuzumab-induced complement dependent cytotoxicity." (PMID 31164885, 2019). "In contrast, levamisole reduces CD59 levels in colon adenocarcinoma cell lines and after pretreatment of breast carcinoma cells with tamoxifen, trastuzumab-induced CDC was enhanced due to CD55 down-regulation." (PMID 31024572, 2019). "Collectively, these results indicate that down-expression of miR-485 facilitates the expression of CD59, thereby improving the proliferation rates and cell migration of breast cancer cells." (PMID 24904649, 2014). "Perhaps the overexpression of miR-1246 alters the CD59 expression profiles in breast cancer, resulting in cell apoptosis." (PMID 24904649, 2014). "When accounting for overall cell number, the relative surface expression level of CD59 and CD55 was observed to increase appreciably in glutamine-restored breast cancer cells, which explains the associated increased complement resistance." (PMID 17623109, 2007). "In breast cancer, CD59 could promote the growth of neoplasm and predict the poorly prognostic status." (PMID 34322132, 2021). "Subsequent studies detected that most solid tumors expressed CD59 at a markedly high level compared to adjacent normal tissues, of which stage and prognosis were related to the CD59 levels, including breast cancer, non-small cell lung cancer, colon cancer, etc.." (PMID 30636930, 2019). "Silencing of CD55 and CD59 in breast cancer cells with specific shRNA enhanced CDC." (PMID 31024572, 2019). "Thus, neutralization of CD59 function with YTH53.1 significantly increased complement-mediated lysis of breast cancer cells." (PMID 17623109, 2007). "Interestingly, neutralization of CD59 in breast cancer cells deprived of glutamine resulted in maximal complement-mediated damage, with lysis of 61% of Bcap37 and 72% of MCF7 cells." (PMID 17623109, 2007). "However, with functional CD59 activity unsynchronized Bcap37 and MCF7 cells demonstrated 26% and 37% complement lysis, respectively, indicating CD59 contributes significantly to complement resistance in unsynchronized breast cancer cells." (PMID 17623109, 2007). "Recent researches about Hepatitis B X-interacting protein (HBXIP) function on the breast cancer cells has been shown that CD55, CD59, and CD46 are up-regulated through p-ERK1/2/NF-jB signaling to protect breast cancer from complement-dependent cytotoxicity." (PMID 22634835, 2012). "Our objective was to determine the specific degree of protection CD59 offers Bcap37 and MCF7 breast cancer cells from antibody-directed complement-mediated damage when simultaneously challenged with glutamine synchronization." (PMID 17623109, 2007).
breast carcinoma (continued). "Our objective was to determine the specific degree of protection CD59 offers MCF7 and Bcap37 breast cancer cells from antibody-directed complement-mediated damage." (PMID 17623109, 2007). "Nonetheless, increased CD59 and CD55 expression protect breast cancer cells form antibody-directed complement activation." (PMID 17623109, 2007). "In many tumor types (lung cancer, breast cancer, pancreatic cancer, kidney cancer), complement proteins C1q, C1s, C3, C4, anaphylatoxins C3a and C5a and their receptors and regulatory proteins (such as factor B, factor H, factor I, CD55 and CD59) are most often overexpressed." (PMID 40596619, 2025). "Similarly, breast carcinoma cells were more easily lysed after treatment with anti-CD59 and anti-CD55 antibodies, but a much higher degree of lysis was achieved when a mixture of anti-CD59, anti-CD55, and anti-CD46 antibodies was used." (PMID 35227072, 2022).